SOX2 (SRY-box transcription factor 2)
Diseases named in the same sentence as SOX2 in open-access papers (continued):
Sharing a sentence is not in itself a finding about the gene and the disease.
glioblastoma (346 papers, 2007 to 2026). The most malignant astrocytic tumor (WHO grade IV). "Through a combination of in silico and in vitro studies, we identified CASCADES, a novel lncRNA that regulates stem cell identity in glioblastoma by acting as a SOX2 super‐enhancer associated lncRNA." (PMID 39323013, 2025). "Nestin, Nanog, Oct4 and Sox2 are genes implicated in the CSCs properties and are overexpressed in glioblastoma." (PMID 40688657, 2025). "The overexpression of SOX2, moreover, is also associated to several kinds of tumors, including glioblastoma." (PMID 39796258, 2025). "Our work identifies CASCADES as a novel super‐enhancer‐associated lncRNA that modulates SOX2 expression in GSCs and thereby maintains the cancer stem cell identity in glioblastoma." (PMID 39323013, 2025). "Nanocurcumin with dendrozum formulation at those concentrations, which reduced cell survival, down-regulated the expression of OCT4 and SOX2 in glioblastoma cells associated with neurological malignancies." (PMID 39055876, 2024). "Previously, TGF-β signalling activity has been found to be upregulated in perivascular niches and closely associated with stemness markers such as Id1, CD44, Sox4 and Sox2, suggesting an underlying inherent plasticity of glioblastoma tumour cells." (PMID 39724753, 2024). "It was observed that the Zika virus’s oncolytic activity against glioblastomas is linked to the expression of SOX2 in these tumors." (PMID 37896752, 2023). "Protein–protein interaction analysis utilising immune-precipitation and mass spectroscopy has also demonstrated the association of HNRNPC and HNRNPA2/B1 with SOX2 in glioblastoma cell lines." (PMID 37444417, 2023). "In cancer, SOX2 expression is increased in samples from several malignancies, including glioblastoma, and high SOX2 levels are associated with the population of tumor-initiating cells and with poor patient outcome." (PMID 33805518, 2021). "The pluripotency transcription factor SOX2 is essential for the maintenance of glioblastoma stem cells (GSC), which are thought to underlie tumor growth, treatment resistance, and recurrence." (PMID 34732716, 2021). "In glioblastoma as another example, elevated SOX2 expression associates with increased cell motility and tumor spreading and is also detected amongst circulating CSC islets." (PMID 31477842, 2020). "Several groups have detected increased SOX2 levels in biopsies of glioblastoma patients, with the highest levels associated with poor outcome." (PMID 27822457, 2016). "Proteomic analysis of the SOX2-interactome in ES cells, as well as medulloblastoma cells and glioblastoma cells, indicates that SOX2 associates in high molecular weight protein complexes with a large and diverse set of nuclear proteins." (PMID 27145457, 2016). "To further evaluate the association of these cells with large ischemic necroses in glioblastoma tissues, we measured the frequency of SOX2+ HIF-1α+ RNApII-S2P-/low cells and compared it with the extent of necrosis in 21 cases of glioblastoma." (PMID 26799577, 2016). "Reduced Sox2 levels in glioblastoma tumor-initiating cells can cause proliferation to cease and a loss of tumorigenicity, while overexpression of Sox2 in pancreatic cancer is correlated with an invasive and metastatic phenotype." (PMID 23599755, 2013). "Lastly, the association of miR-21 with SOX2, a marker for undifferentiated and proliferating cells with up-regulated expression in glioblastomas further underlined the importance of miR-21 for the pathogenesis of these tumors." (PMID 23358700, 2013). "The loss of proliferation ability and tumourigenicity of glioblastoma stem cells was recently demonstrated in vivo after SOX2 silencing." (PMID 23998913, 2013). "Together, these findings argue that modest increases (2- to 3-fold) in SOX2 levels substantially disrupt the in vitro growth of glioblastoma cells and cause dramatic changes in their cell morphology." (PMID 22937156, 2012).
glioblastoma (continued). "Specifically, SOX2 is a TF that controls the differentiation and pluripotency of stem cells and has been linked to the development of several aggressive malignancies, including lung carcinoma and glioblastoma." (PMID 41155227, 2025). "In contrast, PGC-1α knockdown in glioblastoma cells leads to the attenuation of the neoplastic phenotype and loss of stem-like features, which was reflected by reduced expression of the stemness gene SOX2 but prolonged survival of nude mice." (PMID 37370081, 2023). "Moreover, SOX2 down-regulation in glioblastoma mice models is associated with improved survival, inhibition of cell growth, and induction of cell death." (PMID 35701472, 2022). "High levels of SOX2 have been associated with glioblastoma aggressiveness and worse prognosis." (PMID 33924599, 2021). "The relevance of inflammation as an effective host countermeasure against ZIKV infection is emphasized by the sex determining region Y (SRY)-box 2 (SOX2)-dependent susceptibility of glioblastoma stem cells, as SOX2 expression was associated with a reduced innate antiviral response." (PMID 32110999, 2020). "In glioblastoma, SOX2 promoter hypomethylation was associated with SOX2 overexpression." (PMID 32098209, 2020). "It has recently been reported that Plk1 inhibition may promote differentiation of glioblastoma stem cells triggered through loss of SOX2." (PMID 24204733, 2013). "SOX2 is associated with an immature phenotype in CNS teratomas and glioblastomas." (PMID 20126410, 2010). "In parallel to carcinoma, SOX2 is a critical oncogene for neural progenitor cell–derived cancers, such as glioblastoma and medulloblastoma, where it sustains cancer stem cells." (PMID 41266112, 2026). "In glioblastoma, the novel lncRNA CASCADES is enriched in cancer stem cells and regulates stemness by acting as a super‐enhancer‐associated epigenetic regulator of SOX2." (PMID 39323013, 2025). "In human glioblastoma, IL-6 levels are endogenously lower in patients who achieve histological or radiographic responses to ICI, and ICI-resistant glioblastoma has elevated stem cell markers (SOX2, SOX4, SOX13, PTPRZ1), which can be driven by IL-621,58." (PMID 40161763, 2025). "As a core neurodevelopmental transcription factor, SOX2 expression reprograms differentiated glioblastoma cells to acquire GSC phenotype and function." (PMID 40665579, 2025). "Sex-determining region Y box 2 (SOX2) TF—significant in embryonic development—is a key regulator of CSCs in glioblastoma (GBM), a malignant brain tumor with a dismal prognosis." (PMID 41465103, 2025). "By preserving a reservoir of cancer stem cells that contribute to treatment resistance and recurrence, SOX2 promotes tumor growth and the possibility of metastasis in glioblastoma." (PMID 41155227, 2025). "In glioblastoma models, sertraline downregulates SOX2 and β‐catenin, critical transcription factors for maintaining neural stemness and therapy resistance." (PMID 40874450, 2025). "In glioblastoma models, circuits detecting Sox2 and Oct4 activity triggered expression of neural differentiation factors, effectively reprogramming cancer stem cells toward less aggressive phenotypes." (PMID 41614813, 2025). "No negative effect was observed in the use of CBD in neural stem cells (5–15 μM).↓ Sox2 (10 μM).Protective effect against 5 Gy radiation (effective against glioblastoma) at concentrations of 5–15 μM 0.5 h after irradiation." (PMID 39653426, 2025). "Although lactoferrin pre-treated cells overexpress SOX2, we found that the reprogrammed cells differ in proliferation rate from the U-87 glioblastoma cell line, having a different doubling time as well as a specific growth rate." (PMID 39796258, 2025). "While considering glioblastoma, we found SOX2, DUSP6, SLC24A3, KCNIP3, and DPP4 to be differentially the most upregulated, which have previously been found to be effective in glioblastoma formation and prognosis." (PMID 38769480, 2024).
glioblastoma (continued). "The tumorigenic effects of ALKBH5 also appear to induce a TMZ-resistant state via the demethylation of SOX2 transcripts, resulting in increased SOX2 expression and Wnt5a/b glioblastoma proliferation signaling." (PMID 38928445, 2024). "This study provides critical insights into optimizing Zika virus-based treatment for glioblastoma by highlighting the essential role of SOX2 in viral infection and replication." (PMID 40342640, 2024). "Core glioblastoma stem cells (GSC)-associated genes (such as CDK6 and SOX2) were up-regulated by recurrent SEs, thereby maintaining GSC properties and promoting the malignancy of glioblastoma." (PMID 39090713, 2024). "These critical thresholds provide the optimal conditions for SOX2 expression levels and viral bursting sizes to enhance therapeutic efficacy of Zika virotherapy against glioblastoma stem cells." (PMID 40342640, 2024). "Given that SOX2 levels in human glioblastoma stem cells are critical for successful ZIKV infection and replication, our model enables precise prediction of the success rates of ZIKV-targeted GSC lysis." (PMID 40342640, 2024). "The Zika virus has been shown to infect glioblastoma stem cells via the membrane receptor αvβ5, which is activated by the stem-specific transcription factor SOX2." (PMID 40342640, 2024). "Our study aimed to identify the conditions under which SOX2 expression level, viral infection, and replication can reduce or eradicate the glioblastoma stem cells." (PMID 40342640, 2024). "In glioblastoma stem cells, DYRK1A mimics the effect of BMP4, a member of the TGF family of cytokines, reduces cellular SOX2 levels, and promotes the differentiation of glioblastoma stem cells." (PMID 39482615, 2024). "Lastly, further characterization of the enriched stem cell-like state compartment in glioblastomas with a mesenchymal transition revealed an increased abundance of stem cell markers SOX2, PROM-1, and Nestin." (PMID 38244080, 2024). "In this paper, we develop a mathematical ODE model to investigate the effects of SOX2 expression levels on Zika virotherapy against glioblastoma stem cells." (PMID 40342640, 2024). "Sulforaphane also leads to apoptosis in CD133-positive glioma stem cells and dramatically inhibits the survival of CD133-positive and SOX2-expressing glioblastoma spheroids derived from glioblastoma cell lines." (PMID 39407193, 2024). "Conversely, METTL3 facilitated cell survival by stabilizing the mRNA of SRY­box 2 (SOX2) in glioblastoma." (PMID 37919739, 2023). "The growth of murine glioblastoma can be decelerated or stagnated by silencing the METTL3 to inhibit the expression level of SOX2." (PMID 37437245, 2023). "There is evidence that ALKBH5 can enhance SOX2 expression by demethylating the mRNA of SOX2, thereby promoting resistance to Temozolomide in glioblastoma." (PMID 37007161, 2023). "SOX2 is a major regulator of antiviral response and apoptosis and is highly expressed in glioblastoma cells, which explains the predominant lytic action of Zika virus." (PMID 37896752, 2023). "METTL3 is up-regulated in human glioblastoma tissues and induces m6A modification by binding to SOX2 mRNA in 3′UTR." (PMID 37437245, 2023). "TRIM26 interrupts WWP2, a ubiquitin ligase, to prevent SOX2 protein from ubiquitination and degradation in glioblastoma stem cells (GSCs), which maintains the undifferentiated status of GSCs27." (PMID 37604854, 2023). "In malignant cells, GSCs were identified via CD133 and SOX2 using as markers of glioblastoma stem cells." (PMID 37964983, 2023). "In single-cell RNA-Seq data from 28 glioblastoma patients, KLHDC8A was preferentially expressed in neuronal and neoplastic populations, and KLHDC8A expression overlapped with SOX2+ glioblastoma cells." (PMID 36394953, 2023). "The drug down-regulates SOX2 expression in vitro, reduces the formation ability of glioblastoma cells, and blocks GBM xenograft growth in vivo." (PMID 35804976, 2022).
glioblastoma (continued). "In detail, SOX2 has been identified as a target of miR-21 in glioblastoma and has led to the characterization of a high-miR-21/low-SOX2 glioblastoma subtype associated with poor survival outcome." (PMID 35572197, 2022). "There was also evidence that supported the oncogenic role of CDC20 in glioblastoma via regulating SOX-2-dependent transcription." (PMID 35622386, 2022). "Studies have shown that SOX2 plays a crucial role in regulating the chemoresistance of CD133(+) glioblastoma." (PMID 36184801, 2022). "In conclusion, elucidating different mechanisms in migration and invasion as well as the potential of SOX2 re-expression to reverse the mesenchymal subtype into a more proneural subtype, should thus open a strategy to alternative treatments in glioblastoma." (PMID 35701472, 2022). "Both OCT4 and SOX2 expression are detected in glioblastoma stem cells (GSCs), which survive chemical treatment." (PMID 35274101, 2022). "SOX2 plays crucial roles in maintaining the self-renewal potential of normal stem cells in glioblastoma." (PMID 36091384, 2022). "We also show that the cytoskeletal function and malignant properties of glioblastoma cells shift during subtype transitions induced by altered expression of the neurodevelopmental transcription factor SOX2." (PMID 35701472, 2022). "The transcription factor SOX2 has been shown to regulate glioblastoma gene expression, to shift the cells from proneural subtype to mesenchymal subtype, and SOX2 can be suppressed by SFRP229." (PMID 35701472, 2022). "And another study in glioblastoma stem-like cells showed that SOX2 significantly induced the expression of POLD2 by binding to the POLD2 promoter." (PMID 36119494, 2022). "We also analyzed these parameters in highly invasive glioblastoma mesenchymal subtypes and less malignant glioblastoma proneural subtypes after modification of two key genetic elements: SOX2 and SFRP2 recently identified as subtype regulators." (PMID 35701472, 2022). "Circ-ABCC3 influenced the growth of glioblastoma via the miR-770-5p/SOX2 axis and the PI3K/AKT pathway." (PMID 35883576, 2022). "Expression of SFRP2 in cell line U-2987MG resulted in transition to a mesenchymal phenotype with a more specific cytoskeletal organization increasing collective migration and invasion, as SFRP2 has been shown to act as a SOX2 antagonist in glioblastoma cells." (PMID 35701472, 2022). "Remarkably, SOX2 is also directly targeted by miR-429 in glioblastoma multiforme, but in this cancer downregulation of SOX2 inhibits cell proliferation and induces apoptosis." (PMID 36158660, 2022). "A previous study demonstrated that using the ER stressor drug thapsigargin resulted in the increased expression of GRP78, and the reduced expression of SOX2 in glioblastoma patient derived CSCs." (PMID 36482387, 2022). "There are 144 proteins that have been identified using immunoprecipitation (IP)/MS which interact with SOX2 in glioblastoma cell lines." (PMID 35625706, 2022). "Circ-ABCC3 and SOX2 expression were significantly increased in glioblastoma tissues and cells; however, miR-770-5p expression was substantially decreased compared to control groups." (PMID 35883576, 2022). "It was recently described how glioblastoma cells can shift between proneural and mesenchymal subtypes under the influence of two regulatory elements, SOX2 and SFRP2." (PMID 35701472, 2022). "At the protein level, we also analysed the expression of LIF, two known stem cell markers, Nestin and SOX2, as well as cleaved NOTCH1, the expression of which has been linked to glioblastoma proliferation and stemness." (PMID 35203105, 2022). "ZEB1 promotes cancer stemness in glioblastoma, where it is part of an autoregulatory loop together with SOX2 and OLIG2, two transcription factors with well-established functions in neural stem/progenitor cells." (PMID 34433050, 2021).
glioblastoma (continued). "SOX2 is expressed in neurogenic regions in human brain including the subventricular zone and in glioblastoma SOX2 is essential for maintaining a tumor- and sphere forming cell phenotype." (PMID 34021259, 2021). "In a recent study, SFRP2 is found to inhibit sphere formation, cancer stemness and proliferation of glioblastoma cells by acting as an antagonist of SOX2." (PMID 34852024, 2021). "The pluripotency-related transcription factor SRY (sex-determining region Y)-box 2 (SOX2) has been extensively studied in glioblastoma." (PMID 34732716, 2021). "Using a human nuclear antigen-antibody to detect human glioblastoma cells in the mouse brain, we then used confocal microscopy to image tumor cells and SOX2 immunofluorescence intensity in individual cell nuclei." (PMID 34732716, 2021). "The core pluripotency-related transcription factor SRY (sex-determining region Y)-box 2 (SOX2) is highly expressed in glioblastoma relative to the normal brain and indispensable for key GSC phenotypes, including self-renewal and tumor initiation." (PMID 34732716, 2021). "Further, scRNA-seq analysis of IDH-wild-type glioblastomas revealed that SOX2 expression is maintained, albeit at differing levels, across all four defined cellular states and is associated with divergent oncogenic drivers." (PMID 34732716, 2021). "SOX2 has been reported to be highly expressed in most glioblastoma biopsy specimens, with SOX2 expression levels correlating with increased tumor grade and aggressiveness." (PMID 34732716, 2021). "With regard to previous observations of an active PDGFRA signaling loop in glioblastoma we here experimentally show this can be maintained by SOX2, and subsequently turned off by SFRP2, potentially acting via KLF4." (PMID 34021259, 2021). "The E3 ligase CDC20 regulates SOX2 protein level and transcription in glioblastoma, affecting invasion and self-renewal properties." (PMID 33613844, 2021). "Of these, SOX2 is a well-established stem cell master regulator overexpressed in glioblastoma, particularly in the undifferentiated GSC populations." (PMID 33924599, 2021). "Because of the link between ZEB1 and SOX2 in glioblastoma, it is worth comparing the functions of both proteins in adult neurogenesis." (PMID 34433050, 2021). "The verified protein expression of the progenitor markers NES and SOX2 in the adherent primary glioblastoma cell lines established here is indicating that the cells retained at least the ability to dedifferentiate, if not potential stem cell properties." (PMID 33251771, 2021). "KLF4 is higher expressed in mesenchymal, type B, glioblastoma cultures and was here found to act as a SOX2 antagonist." (PMID 34021259, 2021). "LncRNA SOX2OT elevates SOX2 expression through ALKBH5-mediated epigenetic regulation of glioblastoma and promotes temozolomide resistance." (PMID 34178697, 2021). "Experimentally, SOX2-overexpression transitioned culture U-2982 from a mesenchymal to a proneural glioblastoma gene expression subtype." (PMID 34021259, 2021). "We then identify WWP2 as a bona fide E3 ubiquitin ligase that targets SOX2 for proteasomal degradation in GSCs in vitro and glioblastoma cells in vivo." (PMID 34732716, 2021). "In conclusion, this work suggests an important role of SFRP2 in the transition from a proneural to a mesenchymal glioblastoma subtype via suppression of SOX2 during tumor progression." (PMID 34021259, 2021). "In concert with our observed SFRP2-induced pericyte profile, SOX2 expressing glioblastoma cells have been shown in xenograft models to be able to lose SOX2 expression to generate tumor vessel cell structures that resemble pericytes." (PMID 34021259, 2021). "We here show that SFRP2-overexpression decreases CCNE1, CCND1 and CCNB1, and at the same time decreases SOX2 protein and overall cell proliferation in glioblastoma cells." (PMID 34021259, 2021). "Through this combined approach SOX2 was identified to confer a proneural glioblastoma subtype gene expression signature." (PMID 34021259, 2021).